BRAF (B-Raf proto-oncogene, serine/threonine kinase)
Diseases named in the same sentence as BRAF in open-access papers (continued):
Sharing a sentence is not in itself a finding about the gene and the disease.
melanoma (continued). "About 50% of patients with melanoma carry the v-raf murine sarcoma viral oncogene homolog B1 (BRAF) mutation, which causes the overactivation of MAPK/ERK signaling pathway and leads to the occurrence and metastasis of tumors." (PMID 36387162, 2022). "NRAS mutation is the second most common among melanoma patients, yielding a more aggressive phenotype than BRAF mutants." (PMID 35621952, 2022). "Type III inhibitors of MEK1/2 (trametinib, cobimetinib, and binimetinib) are approved as cancer therapeutics, used in the treatment of melanoma and non–small cell lung cancer patients who have mutations in BRAF, in combination with a BRAF inhibitor." (PMID 35830914, 2022). "It is also estimated that 59% of melanomas are associated with the BRAF mutation, significantly more than the overall incidence of mutations in cancers of 8% found in patient-originated melanoma and short-term cultures." (PMID 36551688, 2022). "In other types of cancer, the frequency of BRAF mutations ranges from 80% in malignant melanoma to 1–5% in lung adenocarcinoma and colorectal cancer." (PMID 36275468, 2022). "In BRAF V600 mutated and wild-type melanomas, the OS was 7.9 months (CI: 6.8–9.0) and 5.3 months (4.5–6.3), respectively." (PMID 36497248, 2022). "Many studies have demonstrated an increase of T cells in BRAF-mutated melanomas after MAPK-pathway-inhibitors treatment, even if there is a loss of this increase with the progression of the therapy." (PMID 35628540, 2022). "Further research is needed to understand the crosstalk between rapidly proliferating melanoma cells and T cells to decipher the biological mechanisms underlying the acquired resistance of BRAF/MEK-targeted therapy." (PMID 35058553, 2022). "And even for BRAF-mutated melanoma treated with combined BRAFi/MEKi durable treatment responses are seen in subpopulations with favorable prognostic factors such as normal or low LDH and low volume of disease." (PMID 35109875, 2022). "When the BRAF V600E mutation was introduced into wild-type BRAF melanoma cells, Mps1-associated kinase activity increased 10-fold." (PMID 36276131, 2022). "The most frequent oncogenic mutation for BRAF in melanomas is the substitution of amino acid valine for glutamic acid at position 600 (V600 E), representing 70–90% of BRAF mutations." (PMID 35495634, 2022). "Selective BRAF inhibitor Dabrafenib combined with a selective MAPK kinase (MEK) inhibitor trametinib successfully prolonged the progression-free survival of melanoma patients with BRAFV600E mutations in a phase I/II clinical trials." (PMID 36210843, 2022). "In accordance with the results observed in the present study, another recent study has suggested that DPG has an apoptotic, anti-proliferative, and anti-migratory effect on the melanoma cell line (SK-MEL-28) bearing the BRAF mutation." (PMID 35992881, 2022). "In February 2020, the patient underwent a subcutaneous nodule biopsy that identified a melanoma metastasis harboring the BRAF p.V600E mutation." (PMID 36077693, 2022). "e., lack of response to therapy occurs less frequently (in 10% of BRAF-mutated melanomas) and is thought to be associated with PTEN and MAP2K135." (PMID 35999349, 2022). "Ulixertinib (BVD-523) is a widely used ERK inhibitor for the treatment of NRAS-mutated melanoma and BRAF-mutated solid tumors." (PMID 36233210, 2022). "Further analysis showed that reduced expression of PMCA4b in BRAF mutated melanoma cells is partially due to the increased degradation of PMCA4b induced by elevated activity of the p38 MAPK pathway." (PMID 35328746, 2022). "Dabrafenib and trametinib combination has proven useful in treating malignant melanoma patients harboring a BRAF V600E mutation, improving progression-free survival and overall survival, and it has been tested in other tumors." (PMID 36531075, 2022).
melanoma (continued). "These cumulative responder cases strongly suggest the potential therapeutic benefits of BRAF/MEK inhibition in BRAF p.V600E-mutated ameloblastoma (note: such combination is FDA-approved for BRAF p.V600E-mutated thyroid cancer and melanoma)." (PMID 35296678, 2022). "Melanoma patients bearing the serine/threonine kinase BRAF mutation treated with BRAF and MEK inhibitors exhibited a 70% response rate." (PMID 35163615, 2022). "The same authors utilized a pre-clinical animal model of melanoma (SK-MEL-28) expressing the BRAF (V600E) mutation and found the V600E mutation in the circulating exoDNA isolated from melanoma-bearing mice." (PMID 36556468, 2022). "After the acquisition of resistance to vemurafenib, a drug that targets mutated BRAF, resistant melanoma cells exhibited increased autophagy and increased secretion of ATP." (PMID 35008395, 2022). "Both trials investigated the best possible sequence for patients with therapy-naive stage IV melanoma with a BRAF V600 mutation." (PMID 35885042, 2022). "Consistent with this, we found that several BRAF-mutated melanoma cell lines are more sensitive to CDK12 inhibition (THZ531) (IC50 values between 55 nM and 220 nM) than melanocytes (IC50 > 1 μM)." (PMID 36309522, 2022). "The patient’s melanoma was BRAF V600E mutated, and he had received multiple prior treatments including PD-1 inhibitors, CTLA-4 inhibitor, as well as BRAF/MEK inhibitor combination therapy." (PMID 36104795, 2022). "Melanoma is commonly driven by activating mutations in the MAP kinase BRAF; however, oncogenic BRAF alone is insufficient to promote melanomagenesis." (PMID 35768444, 2022). "Until now, no large volume of real-world data is available on sequencing treatments in patients with BRAF-mutated melanoma, including those with poor prognostic factors." (PMID 35456332, 2022). "For instance, continued treatment with a BRAF inhibitor can cause metastasis of RAS/BRAF-mutant melanoma." (PMID 35603167, 2022). "A randomized (1:1:1) phase III study evaluated the efficacy of binimetinib plus encorafenib in patients with metastatic or unresectable melanoma with BRAF V600E or V600K mutation (Study CMEK162B2301)." (PMID 35742834, 2022). "Melanoma is an aggressive tumor characterized by mutations in the oncogenes BRAF or NRAS, resulting in the overactivation of the MAPK/ERK and PI3K/Akt pathways." (PMID 36060947, 2022). "More than one half of melanomas carry mutations of the gene coding the BRAF kinase, a key upstream component of the MAPK signaling pathway, which is involved in cell growth and proliferation." (PMID 35494017, 2022). "In contrast, truncated forms of mutant BRAF are associated with resistance to BRAF inhibitor treatment as a form of “on-target” therapy resistance in melanoma and lung cancer." (PMID 35579943, 2022). "Several studies demonstrated the prognostic value of ctDNA assessed via ddPCR, as high levels of BRAF V600-mutated ctDNA at melanoma diagnosis correlated with shorter PFS and OS rates." (PMID 35887633, 2022). "This is the first phase III clinical trial aimed at evaluating an immune checkpoint inhibitor combined with BRAF plus MEK inhibitors in patients with advanced BRAFV600 mutation-positive melanoma." (PMID 36358912, 2022). "Our studies then focused on melanoma cells carrying the Q61R NRAS mutation (BLM cells) or the V600E BRAF mutation (A375 cells), representing the main mutations identified in melanoma patients." (PMID 36400750, 2022). "Abnormal activation of BRAF is the most frequently observed mutation event in patients with melanoma and is associated with constitutive hyperproliferation." (PMID 36014370, 2022). "A SOX10-deficient, slow-cycling state has been implicated in acquired resistance of BRAF-mutant melanoma to BRAFi through upregulation of TGFβ1-EGFR signaling." (PMID 35296667, 2022). "In the same year, Trametinib (GSK1120212) was also approved for the treatment of patients with advanced melanoma with the BRAF V600E mutation." (PMID 35912223, 2022).
melanoma (continued). "The presence of BRAF V600E mutation can assist in identifying primary papillary thyroid cancer, but it is also common in melanoma." (PMID 35328664, 2022). "Recent studies have revealed that coincidence of thyroid papillary carcinoma and malignant melanoma is associated with BRAF gene mutation." (PMID 35039080, 2022). "The discovery of the high frequency of mutation in melanoma BRAF protein (over 50% of cases show BRAFV600E) set off the development of target-specific drugs, a strategy that was expected to overcome all barriers of toxicity and resistance faced until then." (PMID 35621952, 2022). "Based on their work, the authors propose a therapeutic protocol starting with checkpoint inhibitors followed by BRAF-inhibitor in BRAF mutated melanoma patients." (PMID 35558554, 2022). "The targeting of the Mitogen-Activated Protein Kinase (MAPK) signalling pathway in melanoma improves the prognosis of patients harbouring the V-Raf Murine Sarcoma Viral Oncogene Homolog B1 (BRAF) mutation." (PMID 35335966, 2022). "For inoperable stage IIIC/IV BRAF-mutated melanoma, combined BRAF and MEK inhibitor therapy is the current gold standard." (PMID 35893303, 2022). "Mutations in BRAF gene are found in diverse types of cancer including melanoma, colorectal adenocarcinoma, non-small-cell lung cancer, papillary thyroid carcinoma and hairy cell leukemia and are considered oncogenic drivers." (PMID 36275468, 2022). "This mutation accounts for about 80% of the BRAF mutations in melanoma and represents one of the major causes of melanoma transformation." (PMID 36009541, 2022). "This is worth highlighting, considering that nearly 50% of melanoma patients have BRAF mutations and can be treated with these drugs, benefiting from a 64–76% objective response rate and a 5-year overall survival rate of 31–35%." (PMID 36233289, 2022). "Mutations in the hedgehog pathway led to the application of smoothened inhibitors for the treatment of basal cell carcinoma and BRAF mutations have been successfully targeted with BRAF inhibitors in melanoma." (PMID 35408839, 2022). "Although BRAF inhibitors and MEK inhibitors are effective in improving overall survival in patients with BRAF-mutated melanoma, a concern remains over the development of resistance and subsequent disease progression." (PMID 35492830, 2022). "Combination therapies, such as Encorafenib (LGX818) with Binimetinib (MEK162), demonstrate long-term efficacy in patients with advanced BRAF V600 mutated melanoma, by blocking the mutated BRAF kinase protein and MEK1/2, respectively." (PMID 35993275, 2022). "BRAF mutations occur in 60% while NRAS mutations occur in 20% of melanoma patients both causing constitutive activation of the MAPK pathway, thereby driving uncontrolled cell proliferation and increasing resistance to cell death." (PMID 35379799, 2022). "For example, acral and mucosal melanomas have fewer BRAF mutations but more frequent KIT mutations, amplifications of CCND1, CDK4, and MDM2, and deletion of SPRED1." (PMID 35706047, 2022). "Both the approved BRAF inhibitors and the immunomodulating antibodies are prone to such resistance with melanoma stem cells (MSC) being implicated in the development of such resistance." (PMID 36076924, 2022). "Clinical use of BRAF inhibitors (BRAFis) has significantly improved the overall survival of melanoma patients with tumors possessing an activating BRAF mutation." (PMID 36551563, 2022). "About half of all melanoma patients harbor an activating BRAF mutation that results in the constitutive activation of the RAF-MEK-ERK signal transduction pathway, which is critical for melanoma development and progression." (PMID 35565212, 2022). "To evaluate the influence of FSCN1 downregulation among the various cellular effects mediated by miR‐143‐3p and miR‐145‐5p, we then performed a loss‐of‐function experiment using FSCN1‐specific siRNAs in BRAF‐mutant parental melanoma cells." (PMID 35156321, 2022).
melanoma (continued). "Single agent and combination therapy with BRAFV600E/K and MEK inhibitors have remarkable efficacy against melanoma tumors with activating BRAF mutations, but in most cases BRAF inhibitor (BRAFi) resistance eventually develops." (PMID 35444937, 2022). "Collectively, these results demonstrate that CDK12 inhibition results in the specific upregulation of AP-1 and NF-κB pathways in BRAF-mutated melanoma cell lines." (PMID 36309522, 2022). "Clinical factors, such as volume and disease sites, serum lactate dehydrogenase levels, and BRAF mutation status, used to select the initial therapy for patients with advanced melanoma have been rather unreliable." (PMID 36613491, 2022). "Aside from primary CNS tumors, BRAF mutations have been implicated in several cancers including melanoma, pancreatic acinar carcinoma and papillary thyroid carcinoma." (PMID 35436952, 2022). "Detection of BRAF V600E mutation in melanoma patients is improved when analyzed in isolated vesicles compared to the reference protocol for ctDNA isolation." (PMID 36704194, 2022). "Because approximately 50% of melanomas harbour an activating mutation in the BRAF gene, several BRAF inhibitors have been developed and adopted as therapeutic agents that are effective against melanoma with BRAF mutations." (PMID 36282887, 2022). "In 40–50% of the patients with advanced melanoma, BRAF gene mutations are present, leading to the continued activation of the mitogen-activated protein kinase (MAPK) signaling pathway and increased cell growth and proliferation." (PMID 35703270, 2022). "Although patients with BRAF-mutant melanoma with brain metastasis had fair local control on BRAF plus MEK inhibitors, the competing risk of death and distant intracranial and extracranial progression in our institutional experience was high." (PMID 36579260, 2022). "Approximately half of patients with melanoma harbor a BRAF gene mutation with subsequent dysregulation of the RAF-MEK-ERK signaling pathway." (PMID 35492830, 2022). "BRAF class 1 mutations occurred predominately in sole (25.4% vs. 2.7%) compared to subungual melanoma, in contrast with CDK4 amplification (5.6% vs. 24.3%)." (PMID 35706047, 2022). "BRAF V600R is the third most common BRAF mutation in malignant melanoma, accounting for approximately 3–7%." (PMID 35380338, 2022). "Almost 50% of all melanomas have a mutation in the BRAF gene, while 15–20% have a mutation in the NRAS gene, which leads to constitutive pathway activation." (PMID 36139698, 2022). "BRAF is commonly associated with clonal mutations in colon, stomach, melanoma and thyroid cancers, especially in melanoma and thyroid cancers." (PMID 35962343, 2022). "Other BRAF mutations, although less frequent, can be found in melanoma, including V600K, V600R, V600D for example." (PMID 35495634, 2022). "A number of mutations related to malignant melanoma (MM) have been identified, and of the mutated genes, BRAF has been found to be altered in > 50% of cases." (PMID 35080260, 2022). "Our in vitro tests demonstrated that blockade of the forward NCX effectively inhibited the growth of melanoma cells which have either BRAF or NRAS mutation." (PMID 35055084, 2022). "A compelling example in melanoma are BRAF mutations which confer increased glycolytic capacity compared to BRAF wild type tumors." (PMID 35912100, 2022). "Dabrafenib and trametinib have certain beneficial effects on ATC, melanoma, and fibrosarcoma patients with BRAF mutations, because they act as BRAF and MEK inhibitors by significantly inhibiting the activation of downstream proteins of the MAPK pathway." (PMID 36430869, 2022). "Only 17% of patients had BRAF-mutated melanoma, probably due to enrolment on a competing neoadjuvant trial specific for patients with BRAF-mutated disease." (PMID 36289334, 2022).
melanoma (continued). "Through further study, we found that lj‐2‐66 exerts antitumour effects in melanoma harboring BRAF mutations both in vivo and in vitro and that the effective concentration was much lower than that of chloroquine." (PMID 35332658, 2022). "Up to now, the second-generation BRAF inhibitors vemurafenib (PLX4032) and dabrafenib (GSK2118436) were approved by the United States Food and Drug Administration (FDA) for the treatment of patients with metastatic melanomas harboring BRAF V600 mutations." (PMID 35910024, 2022). "Single-gene assays for BRAF mutations are extensively used across other cancer types including melanoma." (PMID 35433454, 2022). "combined adenosine A2A receptor (A2AR) antagonist with BRAF and MEK inhibition in melanoma cell lines and murine melanoma BRAF-mutated models." (PMID 36131912, 2022). "Current studies have shown that somatic genetic alterations are associated with melanoma and that the BRAF/RAS/RAF/MEK/ERK signaling pathway is often dysregulated in melanoma." (PMID 36051486, 2022). "The DREAMseq trial recently showed that patients with BRAF V600–mutated advanced melanoma who received nivolumab plus ipilimumab followed by dabrafenib plus trametinib experienced greater OS (72%) compared with patients receiving the converse sequence (52%)." (PMID 35703181, 2022). "BRAF mutations in melanoma are very well known and documented, being described to promote and sustain oncogenesis by inhibition of the apoptosis process and tumor suppressor inactivation." (PMID 35056382, 2022). "As a consequence, co-targeting HER3 and BRAF/MEK appears as an interesting option to overcome therapeutic resistances in BRAF-mutated melanoma." (PMID 35159045, 2022). "Approximately 66% of malignant melanomas have BRAF (B-RAF proto-oncogene) mutations, which lead to an increase in constitutive BRAF kinase activity and the MEK-ERK1/2 pathway and are necessary for proliferation, invasion and survival in melanoma cells." (PMID 36601121, 2022). "Our previous studies highlighted a key role of HO-1 in limiting the efficacy of PLX4032 on BRAF mutated melanoma cells cultured under 18 kPa O2." (PMID 35740068, 2022). "BRAF is a member of the Raf kinase family, and the oncogenic V600E mutation in BRAF has been identified in 90% of melanoma cases, leading to the activation of the MAPK pathway." (PMID 35785205, 2022). "Shorter survival times for patients with class II or III BRAF mutations compared to class I mutations were described for both lung cancer and advanced melanoma [14••, 18••]." (PMID 35380338, 2022). "KRAS mutations are particularly frequent in pancreatic, colorectal, lung cancer, multiple myeloma, whereas NRAS and BRAF mutations are frequent in melanoma." (PMID 36358725, 2022). "It was noticed that the treatment of sorafenib and fisetin together efficiently decreased the migration as well as the invasion of BRAF-mutated melanoma cells." (PMID 36558146, 2022). "The combination therapy resulted in an overall response rate of 58% and a five-year OS rate of 60% in BRAF-mutated melanoma." (PMID 35308763, 2022). "Vemurafenib (a second-generation BRAFi) has already been studied in the treatment of BRAF V600E e V600K mutation-positive melanoma in the BRIM-3 Trial of 337 adult patients." (PMID 35681673, 2022). "Molecular characterization of the complex melanoma landscape confirmed the heterogeneity and high mutational burden of cutaneous melanoma, leading to the classification into four subgroups: mutant BRAF, mutant NRAS, mutant NF1, and triple wild-type (WT)." (PMID 35682659, 2022). "Such variations, like in B-Raf proto-oncogene, serine/threonine kinase (BRAF) in malignant melanoma, occur in all tumor cells and thus have a high variant allele frequency (VAF) of often >1% in cfDNA in the described setting." (PMID 35328301, 2022). "In patients with BRAF V600 E/K mutated melanoma, anti-PD1 is used as an alternative to the BRAFi+MEKi combination in both the adjuvant and therapeutic settings." (PMID 36844955, 2022).